PRF1 (perforin 1)
Diseases named in the same sentence as PRF1 in open-access papers (continued):
Sharing a sentence is not in itself a finding about the gene and the disease.
breast cancer (16 papers, 2017 to 2025). A primary or metastatic malignant neoplasm involving the breast. "Consistent with this role, it has been recently shown that mice deficient in perforin-1 (Prf1-/-) display increased tumor burden in a mammary tumor model." (PMID 33076840, 2020). "We found that SLAMF6 expression was highly correlated not only with the expression of T-cell markers (CD3E, CD8B, CD8A, and CD4) but also with upregulation of TCF7, PDCD1 encoding PD-1, GZMK, and effector-associated genes including IFNG and PRF1 in breast cancer." (PMID 38287061, 2024). "Among cancer patients with stage III and IV ovarian and basal-like breast cancer, PRF1 expression levels correlate with the infiltration of CD8+ T cells, dendritic cells, and neutrophils." (PMID 39199299, 2024). "In breast cancer, PPP2R2B expression was strongly associated with immune check point inhibitor genes such as BZMA, PRF1, and IFNG, suggesting that downregulation of PPP2R2B could take part in tumor immune evasion." (PMID 39851522, 2025). "The combination of the genes IFNG, CXCL13, CD30, and PRF1 clearly predicted favorable outcome in III and IV stage ovarian cancer and in basal-like breast cancer." (PMID 31998644, 2019). "Overall, kidney and breast cancers displayed the highest expression of GZMA, GZMB, GZMK and PRF1." (PMID 40002821, 2025). "Furthermore, IL (including IL-2, IL-15, and IL-18)-induced NK cells inhibited the proliferation of MCF7 cells (NK cells on breast cancer cells) and increased the release of TNF-α, IFN-γ, PRF1, and GzmB." (PMID 39199299, 2024). "Bioinformatics analysis of in silico publicly available TNBC data identified BCL3 and BCL2 as well as the following anti-tumour immune response biomarkers as significantly altered in TNBC compared to other breast cancer subtypes: GZMA, PRF1, CXCL1, CCL2, CCL4, and CCL5." (PMID 38022682, 2023). "One study reported ZNF331 expression in T cell clusters in breast cancer with resident effector memory phenotype co-expressing regulatory elements that may involve in cell cycle regulation and upregulating GZMK over GZMB and PRF1, aligning with our observations." (PMID 40028342, 2025). "Consequently, CD8+ T-cell effector (Teff) score, comprising gene expression of IFNG, PRF1, CD8A and CD8B, and BATF3-DC score, calculated with the expression level of BATF3, IRF8, THBD, CLEC9A, and XCR118 were markedly increased in the high SLAMF6 group than in the low SL AMF6 group in breast cancer." (PMID 38287061, 2024).
viral infection (15 papers, 2014 to 2025). "Our novel variant identified in perforin 1 (PRF1) encodes complement component C9 structural similar protein that assembles into membrane pores in response to virus infection and cancer." (PMID 34070492, 2021). "In this study, we observed 12 different PRF1 mutations in nine patients, most of whom had viral infection at HLH onset." (PMID 25233452, 2014). "In order to explore the importance of CD4+ T cell derived Prf1 for successful host defense in CNS virus infection in vivo, we immunized Prf1 deficient mice (Prf1-/-) with MVA/CFA and established viral encephalitis in CD8+ T cell depleted animals by intrathecal infection with VV." (PMID 24606807, 2014). "Recently, Elgislouli and colleagues observed an alteration of the methylation pattern of a particular enhancer region in the perforin 1 gene (PRF1), an essential cytotoxic protein for the control of viral infection, occurring after severe RSV infection." (PMID 35619695, 2022). "Upregulation of Perforin 1 mediated by CD8-positive T cells after antigen-specific stimulation contributes to the control of viral replication in various viral infections, such as HIV, cytomegalovirus, and adenovirus." (PMID 31511581, 2019). "Considering the role perforin plays in the cellular immune response to virus infections, we hypothesised that severe RSV infection in infancy might be associated with alterations in PRF1 methylation." (PMID 28253869, 2017). "None of the patients with PRF1 gene mutations were positive for the screened viral infections." (PMID 33224420, 2020). "HLH in these patients could be either EBV-driven HLH, secondary HLH or genetic forms of FHL other than FHL2 triggered by infection as none of patients with PRF1 gene mutation in our study were positive for viral infection." (PMID 33224420, 2020). "Gene Ontology (GO) analysis revealed enrichment in immune response pathways, particularly those related to viral infection and type I IFN signaling, in Prf1–/– tumors." (PMID 40627458, 2025). "In Class1, the viral infection pathways (e.g., HSV-1, EBV) and antigen presentation (e.g., HLA-DRB1/DQB1/C, CD74, CTLA4, GZMB, PRF1) were primarily enriched." (PMID 41394852, 2025).
Familial hemophagocytic lymphohistiocytosis (12 papers, 2015 to 2024). Familial Hemophagocytic lymphohistiocytosis (FHL) is a rare primary immunodeficiency characterized by a macrophage activation syndrome (see this term) with an onset usually occurring within a few months or less common several years after birth. "Mutations in PRF1 lead type 2 FHL (Familial hemophagocytic lymphohistiocytosis) which is a rare, rapidly fatal, autosomal recessive immune disorder characterized by uncontrolled activation of T cells and macrophages and overproduction of inflammatory cytokines." (PMID 31311583, 2019). "PRF1 encodes perforin 1, a gene associated with familial hemophagocytic lymphohistiocytosis." (PMID 30573779, 2019). "For example, we detected a heterozygous PRF1 gene synonymous mutation (c.1620A>G, p.Q540Q, MIM# 603553) in patient P63 who was diagnosed with Familial Hemophagocytic Lymphohistiocytosis (FHL)." (PMID 26274329, 2015). "Additionally, and in agreement with a previous report, we also detected rare heterozygous mutations in some genes, including AP3B1, PRF1, LYST and DOCK8, that are associated with familial hemophagocytic lymphohistiocytosis in patients with MIS-C." (PMID 36282598, 2023). "The frequency of mutations in HLH-related genes varies by country, with PRF1 and UNC13D mutations accounting for approximately 55% and 32% of Familial hemophagocytic lymphohistiocytosis (FHL) in Japan, respectively, while UNC13D mutations account for the majority of FHL in Korea." (PMID 34344437, 2021). "Specifically, most patients clustered within the immune dysregulation category were diagnosed with familial hemophagocytic lymphohistiocytosis (FHL) type 2 (n=3/10;30%), type 3 (n=2/10; 20%) and type 4 (n=1/10; 10%), based on homozygotic pathogenic variants in PRF1, UNC13D, and STX11, respectively." (PMID 34992599, 2021). "Human Perforin-1 deficiency causes familial hemophagocytic lymphohistiocytosis, which is lethal if not treated." (PMID 27857713, 2016). "Germline mutations in genes involved in perforin-granzyme-mediated cytotoxicity such as PRF1, UNC13D, STX11, and STXBP2 were known to induce familial HLH (FHL)." (PMID 38404589, 2024).
colon carcinoma (11 papers, 2016 to 2025). "In this study, the average expressions of CD8A, CD8B, GZMA, GZMB, and PRF1 genes were used to represent level of CTL in colon cancers." (PMID 38327746, 2024). "Moreover, PRF1 has also been shown to play a role in the prognosis and progression of various cancers including breast and colon cancer." (PMID 36505419, 2022). "Previous research showed in tumor-infiltrating cytotoxic T lymphocytes (CTLs) in human colon carcinoma that SUV39H1 mediated H3K9me3 marks at the promoters of CTL effector genes (e.g., GZMB, PRF1, FASLG, and IFNG)." (PMID 40059829, 2025). "We identified that in APC-wt/MSS colon cancer, the expressions of PD-1, PD-L1, CTLA4, and CYT (GZMA and PRF1) were increased." (PMID 35937946, 2022). "IP expression also correlated with the expression of CD3E, CD8 and PRF1 in colon cancer, another form of solid tumor infiltrated by TILs21 (data not shown)." (PMID 27659694, 2016).
ovarian carcinoma (11 papers, 2018 to 2025). A malignant neoplasm originating from the surface ovarian epithelium. "NKT cells strongly expressed the GZMB, GZMA, GZMH, and PRF1 genes, indicating that they promoted tumor cytotoxicity in ovarian cancer." (PMID 35935940, 2022). "PRF1 was also confirmed to have close relation with better OS by modulating tumor immunity in cancers like head and neck squamous cell carcinoma, ovarian cancer and basal-like breast tumors, and liver cancer." (PMID 35345444, 2022). "We found that the combined expression of IFNG, CD30, CXCL13, and PRF1 correlated with better overall survival (OS) in advanced stage ovarian cancer." (PMID 31998644, 2019). "Genes related to ICB (CTLA-4, PD-L1, and PD-L2) and cytotoxic lymphocytes (CD8A, GZMA, and PRF1) were all highly expressed in type I and II ovarian cancer." (PMID 32793247, 2018). "The higher expression of PD-L1, CD8A, GZMA, and PRF1 in type I and II ovarian cancer indicated that these patients would tend to gain more benefit from anti-PD-1/PD-L1 therapy." (PMID 32793247, 2018). "We found that, in ovarian cancer, the expression of CXCL13, INFG, CD30, and PRF1 genes predicted favorable prognosis, and that CXCL3, INFG, and PRF1 were associated with an increased infiltration level of CD8+ T cells and dendritic cells and neutrophils within the tumor." (PMID 31998644, 2019). "A similar non-significant association of (individual or simultaneous) high GZMA and PRF1 expression with better effect on patient survival could also be observed in TCGA-MESO, ovarian cancer (GSE13876 and GSE49997), TCGA-STAD, TCGA-THCA, and TCGA-UCEC." (PMID 29515971, 2018). "Currently, although numerous molecular subtyping has been developed in ovarian cancer, such as IFNG, CD30, CXCL13, PRF1 GBP1, and ETV7 CTLA-4, they provided limited prognostic information or are not validated in the clinical samples." (PMID 36157232, 2022). "We found that XBP1 was significantly correlated with key immunity-killing molecules, including FASL, PRF1, IFNG, GZMB, TNFa, and CD40L in ovarian cancer." (PMID 35991556, 2022). "In ovarian carcinoma, the expression of APOBEC3G was positively correlated with T cell infiltration, expression of cytotoxic granzyme and perforin (GZMB and PRF1), and improved clinical outcome." (PMID 34307377, 2021). "The expression of PD-L2, GZMA, and PRF1 in type I and II ovarian cancer was higher than that in type III ovarian cancer." (PMID 32793247, 2018). "Genes related with ICB, including CTLA-4, PD-L2, PD-L1, CD8A, GZMA, and PRF1, were all lowly expressed in type III ovarian cancer." (PMID 32793247, 2018). "In addition, as seen in ovarian cancer, there was also a clear link between the expression of IFNG, CXCL13, CD30, and PRF1 and presence of immune cells within the tumor, including B cells, CD8+ T cells, CD4+ T cells, dendritic cells, and neutrophils." (PMID 31998644, 2019).
lymphoma (10 papers, 2011 to 2023). A malignant (clonal) proliferation of B- lymphocytes or T- lymphocytes which involves the lymph nodes, bone marrow and/or extranodal sites. "Escape from immune surveillance is thought to be the main mechanism possibly explaining the role of PRF1 genetic mutations in the development of leukemia and lymphoma." (PMID 36765901, 2023). "Bi-allelic PRF1 mutations were found in four primary lymphoma patients, who developed cancer beyond the age of 7 years." (PMID 31311583, 2019). "Lymphoma or HLH was reported in two siblings with PRF1 mutations, and then autoimmune lymphoproliferative syndrome and lymphoma in a patient with heterozygous Fas and PRF1 mutations." (PMID 24795715, 2014). "The description of the association between different kind of lymphoma and HLH has been followed by studies reporting the link between monoallelic PRF1 mutations and lymphomas." (PMID 24795715, 2014). "Inherited PRF1 mutations were subsequently described in various types of lymphomas, which suggests that PRF1 protein is involved in the immune surveillance mechanisms preventing tumor growth and/or development." (PMID 21936944, 2011). "However, more recently, inherited PRF1 mutations were subsequently described in various types of lymphomas, suggesting an involvement in the immune surveillance mechanisms preventing tumor growth and/or development." (PMID 36765901, 2023). "One study identified biallelic PRF1 mutations in 4 out of 29 patients with primary lymphoma." (PMID 37187762, 2023). "Finally, we identified two loss-of-function variants (2.1% of the patients) in BLM and PRF1 genes that have been implicated in susceptibility to multiple cancers, mainly leukemias and lymphomas." (PMID 31514334, 2019). "Mutations in the PRF1 gene result in a reduced ability of immune cells to perform their essential immunosurveillance roles, particularly against spontaneous lymphomas, which accounts for the enhanced risk of lymphoma in FHL patients." (PMID 27703456, 2016). "A combination of a heterozygous PRF1 mutation and a FAS mutation was identified in an ALPS patient with aggressive lymphoma." (PMID 37187762, 2023). "Several reports of lymphoma in patients with hypomorphic cytotoxicity defects, e.g. in PRF1 or UNC13D, imply a predisposition to lymphoma." (PMID 37388727, 2023). "A possible predisposing role of PRF1 variants for ALCL was later established, with the finding of mutations in 27% of children with this subtype of lymphoma." (PMID 24795715, 2014). "We indeed observed that Prf1−/− mice display higher propensity to develop lymphomas." (PMID 30575733, 2018). "In addition, there are few research reports on PRF1, but studies have shown that this gene is involved in expression in diseases such as familial hemophagocytic lymphohistiocytosis type 2, aplastic anemia, diabetes, multiple sclerosis, and lymphoma." (PMID 34671419, 2021).
lupus (9 papers, 2012 to 2025). "In systemic lupus erythematosus (SLE), the overexpression of CD11a, CD40L, CD70, KIR2DL4, and PRF1 in T lymphocytes is associated with DNA hypomethylation in promoter regions." (PMID 38473997, 2024). "Meanwhile, decrease in methylation level of several immune-related genes, e.g. TGAL (integrin alpha L chain, CD11a), CD40LG, TNFSF7 (CD70), KIR2DL4, and PRF1, can influence their expression in lupus T-cells." (PMID 29803202, 2018). "Swalhaet al. reported that combining the total genetic risk with the demethylation status of two T cell related loci linked to lupus, KIR2DL4, and PRF1, men may need much more DNA demethylation to achieve similar lupus flares than women." (PMID 34769338, 2021). "For rheumatoid arthritis, systemic lupus erythematosus, ankylosing spondylitis and osteoarthritis diseases, those common factors include TNFSF10, CX3CR1, LY96, TLR5, TXN, TIA1, PRKCH, and PRF1." (PMID 26352601, 2015). "In this work we have determined the transcript expression of five genes that have proved relevant to lupus and we have confirmed previous observations of high expression of three of them: ITGAL, PRF1, and CD70." (PMID 23029299, 2012). "Subsequently, hypomethylation of certain genes have been identified as important in lupus T cells, such as ITGAL (CD11a), CD40LG (CD40L), TNFSF7 (CD70), Killer-cell immunoglobulin-like receptor (KIR2DL4), perforin (PRF1), and CD5 in lupus B cells." (PMID 25566322, 2014). "Hypomethylation in the promoter region of some genes, such as Integrin Subunit Alpha L (ITGAL, Gene ID: 3683), Perforin 1 (PRF1, Gene ID: 5551), and members of Tumor Necrosis Factor Receptor Superfamily (TNFSF5 and TNFSF7, Gene ID: 959 and 970, respectively), were reported in lupus T cells." (PMID 29387007, 2017).
Sepsis (9 papers, 2011 to 2025). Sepsis is defined as life-threatening organ dysfunction caused by a dysregulated host response to infection. "We report a fulminant neonatal FHL2 case associated with biallelic PRF1 variants that initially mimicked sepsis." (PMID 41477640, 2025). "Some studies have found that PRF1 gene expression is reduced in T cells and natural killer cells in patients with sepsis, but the exact mechanism of action still needs to be further clarified." (PMID 39654893, 2024). "Study showed some hub genes (CD2, CD27, GZMA, KLRB1, and PRF1) have been screened out as sepsis biomarkers and all of them were down regulated genes in sepsis, which consistent with our findings." (PMID 39654893, 2024). "They showed that TNF, IL1-β, CD3D and PRF1 gene expressions were significantly different in patients who developed postoperative sepsis in comparison with patients who recovered uneventfully." (PMID 22027436, 2011). "Truncating PRF1 alleles are loss-of-function and align with neonatal-/early-infant-onset FHL2; notably, c.65delC has been reported among recurrent alleles in Chinese cohorts, and neonatal, sepsis-like courses have been described in FHL2." (PMID 41477640, 2025). "HLH is a hyperinflammatory syndrome in which familial (primary) forms arise from biallelic variants in cytotoxic-pathway genes (e.g., PRF1, UNC13D, STX11, STXBP2), and in neonates the presentation may closely mimic sepsis." (PMID 41477640, 2025). "GNLY, GZMB, PRF1, and RASGRP1, which are lysosome-related genes, are closely linked to the prognosis of sepsis and could potentially serve as novel research targets for sepsis, offering valuable insights for the development of lysosome-targeted therapy." (PMID 38057716, 2023). "Compared to bacteraemic NK cells, sepsis NK cells maintained a level of cytotoxicity gene expression, including GZMA and PRF1 (1.03log2FC & 0.53log2FC)." (PMID 41208955, 2025). "In conclusion, the genes GNLY, GZMB, PRF1, and RASGRP1 exhibited significant upregulation in the normal control group and downregulation in the sepsis group, thereby displaying a positive correlation with the prognosis of sepsis patients." (PMID 38057716, 2023). "Survival analysis screened four genes positively correlated with sepsis prognosis, namely GNLY, GZMB, PRF1 and RASGRP1." (PMID 38057716, 2023). "The analysis revealed that GNLY, GZMB, PRF1, and RASGRP1 exhibited high expression levels in the normal control group, while their expression was low in the sepsis group." (PMID 38057716, 2023). "TBX21, GNLY, PRF1, and IL2RB represent the immune status in sepsis." (PMID 41139765, 2025). "Notably, the analysis revealed that GNLY, GZMB, PRF1, and RASGRP1 exhibited significantly higher expression levels in the normal control group compared to the sepsis group (P<0.05)." (PMID 38057716, 2023). "S1PR5, GNLY, CD247, KLRG1, IL-1R2, AUTS2, IL-2Rβ, ARG1, TGFBR3, TLR5 and PRF1 in the top 80 genes in the two modules were located toward the center of the co-expression network, and CD247, IL-2Rβ, TGF-βR3 and IL-1R2 were identified as core genes in sepsis." (PMID 36855106, 2023). "GNLY, GZMB, PRF1, and RASGRP1 are lysosome-related genes that are closely related to the prognosis of sepsis, and may be used as new research targets for sepsis and provide direction for lysosome-targeted therapy." (PMID 38057716, 2023). "In addition, these results are strengthened by a significantly lower cytotoxic module score (calculated using the AddModuleScore function in Seurat V4 using the cytotoxic-related genes GZMH, GZMK, GZMA, GZMB, PRF1, and GNLY) in all sepsis cytotoxic cell subsets compared to bacteraemia and controls." (PMID 41208955, 2025). "Principal component analysis of GZMA, GZMB, CD8A, CD8B, KLRD1, PRF1 and LAG3 gene expression revealed 81% explained variance for the first principal component considering HIV negative and HIV positive sepsis patients." (PMID 26871709, 2016).